AFP (alpha fetoprotein)
Diseases named in the same sentence as AFP in open-access papers (continued):
Sharing a sentence is not in itself a finding about the gene and the disease.
tumor (continued). "Also, a meta-analysis of HCC cases revealed that increased LC3 expression correlated with tumor number, tumor size, liver cirrhosis, TNM stage, vascular invasion, histological grade, expression of alpha-fetoprotein, and HBsAg." (PMID 33976943, 2021). "In addition to commonly used tumor markers such as CEA, AFP, CA125, CA153 and CA199, heat shock protein 90 alpha (HSP90α) is a broad-spectrum tumor marker worthy of attention in recent years." (PMID 34307453, 2021). "On univariate analysis including each preoperative variable, we found an association between outcomes (both OS and DFS) and the number of tumors, largest tumor size, BCLC stage, CTCs (≥2) and CTC clusters (>0), alpha fetoprotein (AFP) levels, MVI, and TNM stage." (PMID 34722281, 2021). "Twelve-year post-surgical resection follow-up with serial serum alpha-fetoprotein (AFP) tumor marker levels and CT scan of the thorax showed no recurrence." (PMID 34484723, 2021). "Furthermore, IHC staining showed that tumours in the Mettl1‐cKO mice had lower percentage of Ki67‐positive cells and decreased intensity of HCC marker AFP." (PMID 34898034, 2021). "We found that increasing serum GGT levels were not only significantly associated with decreasing survival, but also with significantly worse levels of the 4 tumor parameters-MTD, tumor multifocality, serum AFP levels and percent of patients with macroscopic PVT." (PMID 34540270, 2021). "In AFP-negative Hepa129-tumors a clear difference in tumor size and survival for both i.t.-Ad-CD40L-DC-treated mice independent of vaccination compared to untreated mice was also observed." (PMID 34282787, 2021). "During the follow-up period (range, 2.1–14.2 months), all patients were alive with normal daily activities, and three patients with HCC did not experience tumour recurrence with a normal alpha-fetoprotein level." (PMID 35185367, 2021). "If no residual or recurrent tumor was shown, contrast-enhanced CT or MR and laboratory tests (including blood routine, liver, and kidney function, AFP level, coagulation function, etc.)were performed every 3 months." (PMID 33738247, 2021). "AFP, alpha‐fetoprotein; ALB, albumin; ALT, alanine aminotransferase; AST, aspartate transaminase; CI, confidence interval; HBsAg, hepatitis B surface antigen; SNRPC, expression in tumor nucleus; TBIL, total bilirubin." (PMID 33934562, 2021). "Furthermore, after analyzed the clinical and pathological features of HCC patients in the TCGA dataset, the results showed that the WDR69 methylation level was higher in HCC tumor tissues with high histological grade, AJCC stage, and AFP levels." (PMID 33634306, 2021). "In our cohort, we observed an association between some variables (abnormal post-chemotherapy AFP, tumor relapse after primary therapy, non-surgical management, and non-seminomatous histology) and an adverse survival prognosis." (PMID 35047390, 2021). "Interestingly, our case showed slight evaluated level of CA-125, AFP, and CEA which indicates a tumor lesion." (PMID 33578605, 2021). "GPER immunostaining in tumor cells was significantly associated with sex (P = 0.043), negative HBsAg (P = 0.036), small tumor size (P = 0.002), and low serum AFP levels (P = 0.014)." (PMID 33767999, 2021). "The Cox multivariable analysis indicated that HBV-DNA, GGT level, AFP level, tumor size, tumor differentiation, MVI, satellite nodules, and blood loss were significantly associated with PHER." (PMID 33726693, 2021). "The AFP serum values showed a significant stepwise increase from patients with advanced fibrosis without HCC to patients with advanced tumor (BCLC = B, C and D) (p < 0.001)." (PMID 34064999, 2021).
tumor (continued). "In the present case, ramucirumab did not decrease tumor volume but dramatically reduced AFP level, and the tolerance was better for ramucirumab than for sorafenib and lenvatinib." (PMID 33978943, 2021). "Human chorionic gonadotropin-β and α-fetoprotein (AFP), serum tumor markers, were not measured, as a diagnosis of YST was not suspected at the preoperative stage." (PMID 34804928, 2021). "An abnormal AFP level has been associated with poor outcome in patients with HAL and other hepatoid ADCs; however, the AFP elevation in serum and higher AFP expression in tumor tissues are not necessary criteria for HAL diagnosis." (PMID 33585692, 2021). "Indeed, several clinical and laboratory factors, such as tumor etiology, Child–Pugh score, alpha-fetoprotein (AFP), platelets and gamma-glutamyl transferase have been proposed as predictors of tumor progression and survival in patients on Sorafenib." (PMID 34072309, 2021). "A-fetoprotein (AFP) specific CD8+ T cell clusters, deprived from human leukocyte antigen (HLA)-A2 transgenic AAD mice, were hybridized to generate CD8+ T cell with HLA-A2/AFP identifiable TCR, and the hybridoma T cell clones were detected to have effective toxicity on HCC tumor cells." (PMID 34372912, 2021). "However, LDL subgroups had significant differences in 2 out of 4 of their tumor characteristics, namely in MTD and AFP levels (p=0.003 and 0.05 respectively), with percent of patients with PVT approaching significant differences p=0.08)." (PMID 34457356, 2021). "Correlation with clinical and histologic findings indicates functional relevance and highlights the combined CAD–CPS1 score as an independent prognostic biomarker, especially in early tumor stages and in AFP-negative tumors." (PMID 33670206, 2021). "Moreover, we employed propensity-score matching for liver function (Child–Pugh score and ALBI grade) and tumor status (BCLC stage and AFP level) to compare the OS benefit among patients receiving or not receiving regorafenib therapy." (PMID 34359658, 2021). "Among the staging systems that do not include AFP to correlate radiological and clinical patient characteristics with tumor biology, BCLC showed good results in our cohort." (PMID 33294952, 2021). "Numerous clinical features, including tumor size, edge smoothness, capsule, tumor peripheral enhancement, multifocality, apparent diffusion coefficient (ADC), alpha-fetoprotein (AFP), 18F-deoxyglucose (18F-FDG), have been shown to be helpful for the preoperative prediction of MVI." (PMID 33854959, 2021). "Since AFP is not sensitive and specific enough in early diagnosis of HCC, we need to rely on two or more tumor markers to improve the diagnostic efficiency." (PMID 33971914, 2021). "An additional discrepancy in tumor screening guidelines among recommendation groups includes the use of AFP screening, with this ‘screening measure/tool’ not included within the ICG-BWSp recommendations, with justification that abdominal U/S would detect a HB." (PMID 34828445, 2021). "In addition, tumor size, BCLC-B sub-classification, AFP and ALB levels, as well as number of lesions exhibited the highest VIMP and lowest minimal depth, indicative of strong predictive performance." (PMID 33738252, 2021). "Recent studies have found that AFP and ICAM-1 also play an important role in tumor prognosis." (PMID 34696675, 2021). "Compared with the GPER-negative patients, the GPER-positive patients with HCC were closely associated with female sex, negative hepatitis B surface antigen, small tumor size, low serum alpha fetoprotein level, and longer overall survival." (PMID 33767999, 2021). "These efforts expanded the Milan criteria, which depend on the strict tumor size and number of nodules to determine an HCC patient’s eligibility for LT, to depend on overall tumor size and number of nodules as well as different tumor markers such as AFP." (PMID 34638395, 2021).
tumor (continued). "In the dataset, there was data lacking on liver function parameters, AFP level, tumor location (i.e., perivascular, exophytic), details of surgical techniques, surgeons’ experience level, details of complications, and cause of death." (PMID 34638285, 2021). "Particularly, for patients in BCLC stage C, with HBV infection, without HCV infection, with EHM, without MVI, with tumor size <6 cm or with AFP level <200 ng/ml, lenvatinib significantly prolonged PFS compared with sorafenib." (PMID 34760699, 2021). "We believe, this expansion was due to no cutoff of tumor number, and liberal expansion on tumor size if AFP was <600 ng/ml." (PMID 34295467, 2021). "In addition, AFP can inhibit the expression of death receptor 3 (DR3), and bind with caspase-3, resulting in inhibition of apoptosis of tumor cells induced by tumor necrosis factor-related apoptosis-inducing ligand (TRAIL)." (PMID 33718192, 2021). "The clinical definition of stage IA and IB is the absence of metastatic lesions on imaging and normalized tumor markers (AFP, HCG, and lactate dehydrogenase [LDH]) after orchiectomy." (PMID 33996471, 2021). "In univariate analyses, age >60 years, intrahepatic maximal tumor size of ≤5 cm, absence of extrahepatic metastasis, AFP levels ≤1000 ng/mL, and Child–Pugh class A were factors associated with favorable OS." (PMID 34575160, 2021). "Additionally, CCT5 mRNA was significantly overexpressed in HCC patients with alpha-fetoprotein (AFP) > 300 ng/ml, BCLC staging B-C, TNM staging III and main tumor size > 5 cm (all P < 0.05)." (PMID 34522182, 2021). "Prior data suggest that baseline circulating plasma AFP and TGF‐β1, AFP and TGF‐β1 response kinetics, and tumor SMAD complex activity might discriminate a sensitive HCC subset." (PMID 33811482, 2021). "Blood tests only revealed elevated alpha fetoprotein (AFP) levels, at 14.1 ng/ml (normal: ≦10.0 ng/ml), with no other tumor markers or antiacetylcholine receptor (AChR) antibody noted." (PMID 33960662, 2021). "The presence of at least three out of five criteria (AFP > 1000 ng/dL, Venous expansion, thrombus Enhancement, Neovascularity, and Adjacent to HCC) had 100% sensitivity and 94% specificity in the diagnosis of tumour portal vein thrombosis." (PMID 34944957, 2021). "Regarding tumor-associated factors, tumor size, hilar nodal metastasis, distant metastasis, PVT, and AFP (Alpha-fetoprotein) were not different between the PD and non-PD groups, either." (PMID 33807219, 2021). "Other factors such as age, AFP, PIVKA-II, tumor grade, tumor size, peri-tumor parenchymal enhancement in the arterial phase, unsmooth tumor margins, peri-tumor hypointensity in the hepatobiliary phase, and ADC values have been reported to be significantly associated with early tumor recurrence." (PMID 34026632, 2021). "Patients should also be aware that the prognosis of a non-AFP secreting HCC is not substantially different from an AFP-secreting tumor and post-treatment surveillance similarly consists of serial abdominal and often chest imaging." (PMID 36090909, 2021). "Most early stage HCCs are AFP negative in European studies, making this marker alone inadequate for early tumor recognition." (PMID 34451832, 2021). "In addition, AFP level can predict the expression of hepatic progenitor cell markers as EpCAM in HCC and is correlated with tumor metastasis." (PMID 35070966, 2021). "The variables associated with worse survival prognosis in mediastinal NSGCT in our study include abnormal post-chemotherapy AFP, tumor relapse after primary therapy, and non-surgical management." (PMID 35047390, 2021).
tumor (continued). "We first conducted internal validation of the prognostic model based on the clinical characteristics of the TCGA cohort such as the presence of a new tumour after initial treatment, individual tumour status, AJCC stage, histological grade, vascular invasion and AFP levels." (PMID 33300278, 2021). "However, the commonly used tumor biomarkers such as serum carcinoembryonic antigen (CEA), alpha fetoprotein (AFP) and carbohydrate antigens have disadvantages such as poor sensitivity and specificity." (PMID 33562269, 2021). "Regarding the changes during LEN treatment, tumor size was positively correlated with DCP but not with AFP." (PMID 34174931, 2021). "Univariate analysis demonstrated that AJCC stage, tumor size, grade, surgery and radiotherapy were associated with CSS in the non-chemotherapy group, and AJCC stage, tumor size, AFP, fibrosis score, grade, surgery and radiotherapy in the chemotherapy group." (PMID 34887446, 2021). "The results of the multifactorial analysis revealed that the independent factors for differentiating HAS from non-HAS were serum AFP level, M stage, and tumor enhancement on CT." (PMID 34956891, 2021). "Correlations between serum AFP and 89Zr-DFO-αGPC3 immuno-PET tumor volume remained strong after RIT suggesting 89Zr-DFO-αGPC3 immuno-PET may be useful in assessing response to therapy." (PMID 33580090, 2021). "Even when circulating serum AFP levels were effectively suppressed, complete tumor ablation was not achieved, and subsequent attempts to confirm the effectiveness of antiAFP antibodies were only a partial success." (PMID 34680245, 2021). "Similarly, similar results were found in the validation cohort (CTC:P = 0.007; AFP:P = 0.001; DCP:P = 0.005; Number of tumors:P = 0.003; Maximum tumor diameter:P = 0.037)." (PMID 33859298, 2021). "Comparing sensitivities for methylated genes vs. methylated genes plus tumor-specific protein markers (CEA, AFP, CA19-9), an increase was observed (from 35.3 to 47.1% for stage 0+I, 48.6 to 74.3% for stage II, 64.0 to 80% for stage III, and 89.7 to 96.6% for stage IV)." (PMID 34638449, 2021). "Moreover, histological analysis revealed that tumours in the Mettl1‐KI mice have higher percentage of Ki67‐positive cells and increased intensity of HCC marker AFP, suggesting the higher proliferative activity in the tumours from the KI mice." (PMID 34898034, 2021). "One animal in the 90Y-DOTA-αGPC3 group was not imaged, with moderate sized tumor by serum AFP (95,000 ng/mL)." (PMID 33580090, 2021). "Overexpression of miR-652-3p was remarkedly correlated with clinical TNM stage (P = 0.020) and degree of differentiation (P = 0.031), but not correlated with age, gender, tumor size, AFP, Cirrhosis, smoking status, or alcohol intake (P > 0.05)." (PMID 34608826, 2021). "Serum AFP is widely used in clinical practice for diagnosis, pretreatment prognosis, predicting survival after transarterial chemoembolization, and tumor response to therapy, as it is considered to continuously reflect HCC tumor activity and viable burden." (PMID 34298750, 2021). "As AFP also interacted with RARα and perturbed RA-RAR signaling as well as the anti-tumor effect of ATRA in HCC cells, whether this perturbation also participates in regulation of cell autophagy is of great interest to be investigated." (PMID 33495541, 2021). "Only 1/42 (2.4%) patient did not have elevated AFP at the time of tumor recurrence (AFP normal range: 0–20 ng/mL), and the histological type of the patient was epithelial (mixed fetal and embryonal subtype) after the first and second surgeries." (PMID 34843510, 2021). "The use of tumor markers (especially alpha-fetoprotein, AFP) alone is currently not recommended for HCC screening, but the combination of AFP and B-mode US is endorsed by Eastern countries." (PMID 33668839, 2021).
tumor (continued). "Xenograft tumor of HCT 116 showed an increased expression of neuronal genes MAP2 and SYN1, neural stemness genes CDH2, MSI1, NCAM1, SOX2/9, VIM and ZEB2, and genes for mesodermal and endodermal tissues (ACP5, AFP, DESMIN, HNF4A and KRT8)." (PMID 33468253, 2021). "Serum AFP concentration has been incorporated into patient subclassification, but, to our knowledge, tumor type was not." (PMID 34204125, 2021). "In particular, lenvatinib had a preferred role on better PFS for those patients in BCLC stage C, with HBV infection, without HCV infection, with EHM, without MVI, with tumor size <6 cm, or with AFP level <200 ng/ml." (PMID 34760699, 2021). "Besides, we observed plasma microRNA status changed positive ahead of AFP and DCP increase or imaging examinations upon tumor recurrence." (PMID 34729120, 2021). "In contrast, none of the sex difference, tumor size, total tumor number, AFP or fibrosis score have significant influence on patients’ survival." (PMID 34006241, 2021). "Overall, CMFs could improve the survival duration of 6 months, 1 year, and 2 years, Karnofsky Performance Status, tumor objective response rate (ORR), AFP, and symptom." (PMID 34776950, 2021). "We found a relationship between PNI and AFP, but not the other tumor biological statuses as assessed using tumor stage or histological findings." (PMID 33129309, 2020). "In this study, SEPC levels demonstrated a positive correlation with AFP levels, indicating that SEPCs could be a potential target in HCC diagnosis by acting as a complementary tumour marker." (PMID 33312206, 2020). "For several cancer types, blood-based tumor markers, such as PSA, AFP and CA125 have been introduced into clinical practice and research for the identification of further noninvasive biomarkers applicable for monitoring a wider scale of malignant diseases is ongoing." (PMID 32731530, 2020). "As a tumour marker for the diagnosis of HCC, PIVKA-II has a higher diagnostic value than AFP14,23, particularly for AFP-negative HCC or early-stage HCC24–26." (PMID 32782270, 2020). "Also, aggressive tumor phenotypes such as advanced BCLC stages, high levels of AFP, present vascular invasion and poor differentiation were associated with low KLF4 expression." (PMID 32756012, 2020). "Finally, single-cell suspension from tumour tissues was subjected to flow cytometry to assess the liver CSC markers, such as AFP, GPC3, CEA and CD44." (PMID 32203212, 2020). "Alpha-fetoprotein (AFP), an established clinical biomarker of HCC, has been employed as an attractive target for T cell-based immunotherapy against this disease given its high expression in the tumor and restricted expression in normal tissues." (PMID 32425926, 2020). "Multivariate analysis revealed that the association of a high density of CD4+ T cells with unfavorable OS (HR = 1.480, 95% CI = 1.009 - 2.173, P = 0.045) was independent of AFP level, tumor size, tumor differentiation, microvascular invasion, and TNM stage." (PMID 33552954, 2020). "The differences in age and tumor location between the two groups were not statistically significant (P > 0.05), but the difference in sex, tumor volume, and AFP level were statistically significant (P < 0.05)." (PMID 33330062, 2020). "Residual tumor biopsies were performed in three children after HDCT, and viable tumor cells were found in two patients showing radiological progression with elevated AFP." (PMID 33352733, 2020). "In this study, we evaluated the performance of AFP and PIVKA-II for the diagnosis of HBV-related HCC and explored the relationship between them and different clinicopathologic features, such as vascular invasion, tumor differentiation and size." (PMID 33292429, 2020). "The median tumor size was 32 mm (10–127 mm), and 40.7% of patients (72/177) were classified as BCLC stage C. Median alpha-fetoprotein (AFP) levels were 51.2 ng/mL (1.0–146,260 ng/mL) and des-gamma-carboxy prothrombin (DCP) levels were 233.5 mAU/mL (3.3–524,068 mAU/mL)." (PMID 32664489, 2020).